PTGS2 (prostaglandin-endoperoxide synthase 2)
Description:
Dual cyclooxygenase and peroxidase in the biosynthesis pathway of prostanoids, a class of C20 oxylipins mainly derived from arachidonate ((5Z,8Z,11Z,14Z)-eicosatetraenoate, AA, C20:4(n-6)), with a particular role in the inflammatory response. The cyclooxygenase activity oxygenates AA to the hydroperoxy endoperoxide prostaglandin G2 (PGG2), and the peroxidase activity reduces PGG2 to the hydroxy endoperoxide prostaglandin H2 (PGH2), the precursor of all 2-series prostaglandins and thromboxanes. This complex transformation is initiated by abstraction of hydrogen at carbon 13 (with S-stereochemistry), followed by insertion of molecular O2 to form the endoperoxide bridge between carbon 9 and 11 that defines prostaglandins. The insertion of a second molecule of O2 (bis-oxygenase activity) yields a hydroperoxy group in PGG2 that is then reduced to PGH2 by two electrons. Similarly catalyzes successive cyclooxygenation and peroxidation of dihomo-gamma-linoleate (DGLA, C20:3(n-6)) and eicosapentaenoate (EPA, C20:5(n-3)) to corresponding PGH1 and PGH3, the precursors of 1- and 3-series prostaglandins. In an alternative pathway of prostanoid biosynthesis, converts 2-arachidonoyl lysophopholipids to prostanoid lysophopholipids, which are then hydrolyzed by intracellular phospholipases to release free prostanoids. Metabolizes 2-arachidonoyl glycerol yielding the glyceryl ester of PGH2, a process that can contribute to pain response. Generates lipid mediators from n-3 and n-6 polyunsaturated fatty acids (PUFAs) via a lipoxygenase-type mechanism. Oxygenates PUFAs to hydroperoxy compounds and then reduces them to corresponding alcohols. Plays a role in the generation of resolution phase interaction products (resolvins) during both sterile and infectious inflammation. Metabolizes docosahexaenoate (DHA, C22:6(n-3)) to 17R-HDHA, a precursor of the D-series resolvins (RvDs). As a component of the biosynthetic pathway of E-series resolvins (RvEs), converts eicosapentaenoate (EPA, C20:5(n-3)) primarily to 18S-HEPE that is further metabolized by ALOX5 and LTA4H to generate 18S-RvE1 and 18S-RvE2. In vascular endothelial cells, converts docosapentaenoate (DPA, C22:5(n-3)) to 13R-HDPA, a precursor for 13-series resolvins (RvTs) shown to activate macrophage phagocytosis during bacterial infection. In activated leukocytes, contributes to oxygenation of hydroxyeicosatetraenoates (HETE) to diHETES (5,15-diHETE and 5,11-diHETE). Can also use linoleate (LA, (9Z,12Z)-octadecadienoate, C18:2(n-6)) as substrate and produce hydroxyoctadecadienoates (HODEs) in a regio- and stereospecific manner, being (9R)-HODE ((9R)-hydroxy-(10E,12Z)-octadecadienoate) and (13S)- HODE ((13S)-hydroxy-(9Z,11E)-octadecadienoate) its major products (By similarity). During neuroinflammation, plays a role in neuronal secretion of specialized preresolving mediators (SPMs) 15R-lipoxin A4 that regulates phagocytic microglia (By similarity).
Synonyms: COX-2; PGHS-2; COX2; GRIPGHS; PGG/HS; PHS-2; hCox-2
Tractability: Small molecule: an approved drug acts on it; a structure with a bound ligand is known; a high-quality ligand is known; it belongs to a druggable protein family. Antibody: UniProt places it where antibodies can reach, with medium confidence; UniProt predicts a signal peptide or a membrane-spanning region. PROTAC: ubiquitination databases record sites on it; a small molecule that binds it is known. Other modalities: an approved drug acts on it.
Target class: Enzyme; Oxidoreductase
Chemical probes: PD083141, PD134460, TRYPTANTHRIN
Safety:
Unwanted effects reported when the protein is acted on. In parentheses: how it was acted on, where the effect was seen, and who reports it.
atherothrombosis (Lynch et al. (2017): inhibition, acute dosing, renal, immune, cardiovascular; Bowes et al. (2012): inhibition, cardiovascular system, Immune)
increased blood pressure (Lynch et al. (2017): inhibition, chronic dosing, renal, immune, cardiovascular; Bowes et al. (2012): inhibition, cardiovascular system, Immune)
myocardial infarction (Bowes et al. (2012): inhibition, cardiovascular system, Immune; Urban et al. (2012): inhibition, cardiovascular system)
Decrease, Population growth rate (inhibition; source: AOP-Wiki)
Reduced, Reproductive Success (inhibition; source: AOP-Wiki)
anti-inflammatory activity (inhibition; cardiovascular system, Immune; source: Bowes et al. (2012))
anti-mitogenic effects (inhibition; cardiovascular system, Immune; source: Bowes et al. (2012))
antiinflammatory (inhibition; cardiovascular system; source: Urban et al. (2012))
atherosclerosis (inhibition, chronic dosing; renal, immune, cardiovascular; source: Lynch et al. (2017))
cerebrovascular events (inhibition; cardiovascular system; source: Urban et al. (2012))
clotting (inhibition; cardiovascular system; source: Urban et al. (2012))
decreased inflammation (inhibition, acute dosing; renal, immune, cardiovascular; source: Lynch et al. (2017))
decreased mitosis (inhibition, acute dosing; renal, immune, cardiovascular; source: Lynch et al. (2017))
decreased pain (inhibition, acute dosing; renal, immune, cardiovascular; source: Lynch et al. (2017))
decreased urinary potassium excretion (inhibition, acute dosing; renal, immune, cardiovascular; source: Lynch et al. (2017))
decreased urinary sodium excretion (inhibition, acute dosing; renal, immune, cardiovascular; source: Lynch et al. (2017))
heart attack (inhibition, acute dosing; renal, immune, cardiovascular; source: Lynch et al. (2017))
heart failure (inhibition; cardiovascular system; source: Urban et al. (2012))
hypotension (inhibition; cardiovascular system; source: Urban et al. (2012))
increased risk of wound infections (inhibition; cardiovascular system; source: Urban et al. (2012))
inhibits some mitogenic actions (inhibition; cardiovascular system; source: Urban et al. (2012))
ischaemic stroke (inhibition; cardiovascular system, Immune; source: Bowes et al. (2012))
ischemic stroke (inhibition, acute dosing; renal, immune, cardiovascular; source: Lynch et al. (2017))
N/A, Reproductive failure (inhibition; source: AOP-Wiki)
supraventricular tachycardia (inhibition; cardiovascular system; source: Urban et al. (2012))
thrombosis (inhibition, chronic dosing; renal, immune, cardiovascular; source: Lynch et al. (2017))
hypercholesteremia (source: ClinPGx)
Gene: Protein-coding gene on chromosome 1 (186,671,791 to 186,680,922, reverse strand). Ensembl gene ENSG00000073756.
Subcellular location: Microsome membrane; Endoplasmic reticulum membrane; Nucleus inner membrane; Nucleus outer membrane
Subcellular location (Human Protein Atlas): Vesicles; Cytosol
Pathways (Reactome):
Metabolism: Biosynthesis of DHA-derived SPMs; Biosynthesis of DPAn-3 SPMs; Biosynthesis of EPA-derived SPMs; Biosynthesis of electrophilic ω-3 PUFA oxo-derivatives; Synthesis of 15-eicosatetraenoic acid derivatives; Synthesis of Prostaglandins (PG) and Thromboxanes (TX)
Immune System: Interleukin-10 signaling; Interleukin-4 and Interleukin-13 signaling
Gene Ontology:
Molecular function: enzyme binding; oxidoreductase activity, acting on single donors with incorporation of molecular oxygen; prostaglandin-endoperoxide synthase activity; protein binding; heme binding; peroxidase activity; oxidoreductase activity, acting on paired donors, with incorporation or reduction of molecular oxygen; protein homodimerization activity
Biological process: cellular response to hypoxia; cyclooxygenase pathway; prostaglandin biosynthetic process; lipoxygenase pathway; long-chain fatty acid biosynthetic process; positive regulation of brown fat cell differentiation; positive regulation of cell migration involved in sprouting angiogenesis; positive regulation of fever generation; positive regulation of fibroblast growth factor production; positive regulation of nitric oxide biosynthetic process; positive regulation of platelet-derived growth factor production; positive regulation of prostaglandin biosynthetic process; positive regulation of transforming growth factor beta production; positive regulation of vascular endothelial growth factor production; regulation of blood pressure; regulation of inflammatory response; regulation of neuroinflammatory response; brown fat cell differentiation; cellular oxidant detoxification; cellular response to non-ionic osmotic stress; negative regulation of apoptotic process; negative regulation of intrinsic apoptotic signaling pathway in response to osmotic stress; prostanoid biosynthetic process; response to oxidative stress
Cellular component: cytoplasm; endoplasmic reticulum; endoplasmic reticulum membrane; neuron projection; nuclear inner membrane; nuclear outer membrane; endoplasmic reticulum lumen
Genetic constraint (gnomAD): Loss-of-function variants: 13 observed, 62.67 expected, observed/expected ratio (o/e) 0.21, 90% interval 0.13 to 0.33. The upper end of that interval is the gene's LOEUF score, 0.33, which puts it in group 1 of 6, group 1 being the genes least tolerant of losing a copy. Missense variants: 532 observed, 766.21 expected, observed/expected ratio (o/e) 0.69, 90% interval 0.65 to 0.75. Synonymous variants: 271 observed, 268.61 expected, observed/expected ratio (o/e) 1.01, 90% interval 0.91 to 1.12.
Homologues: Orthologues: chimpanzee PTGS2 (99% identical), macaque PTGS2 (98% identical), dog PTGS2 (90% identical), rabbit PTGS2 (90% identical), pig PTGS2 (90% identical), guinea pig PTGS2 (88% identical), mouse Ptgs2 (87% identical), rat Ptgs2 (86% identical), tropical clawed frog ptgs2 (74% identical), zebrafish ptgs2b (74% identical), zebrafish ptgs2a (68% identical). Paralogues in human: PTGS1 (61% identical).
Diseases named in the same sentence as PTGS2 in open-access papers:
PTGS2 is named in the same sentence as 611 diseases in open-access papers, as found by Europe PMC text mining. Sharing a sentence is not in itself a finding about the gene and the disease. The quoted sentences say what the papers report.
breast carcinoma (224 papers, 2003 to 2026). "Our results disclosed that higher expression of PTGS2/ESR2/EGFR/JUN/MMP2 genes’ signature associated with the most aggressive breast cancer subtypes donating by basal breast cancer (P < .00001) and the ER-negative breast tumors ( P < .00001)." (PMID 39707884, 2024). "Five proteins (i.e., EGFR, MAPK3, ESR1, MAPK1, and PTGS2) associated with breast cancer were selected as receptor proteins." (PMID 38794187, 2024). "Ablation of the Ptgs2 gene (encoding COX-2) in fibroblasts reversed the immune-suppressive phenotypes of lung myeloid cells in multiple breast cancer models." (PMID 38332913, 2023). "The most frequent polymorphisms in PTGS2, which are associated with the development of gastric cancer, colorectal cancer, bladder cancer and breast cancer, are located in the promoter regions −1195G > A (rs689466) and −765 G > C (rs20417)." (PMID 34209679, 2021). "PTGS2, a polymorphic gene, encodes cyclooxygenase-2 (COX-2) which is overexpressed in breast cancer and is related to invasive parameters such as tumor size, angiogenesis, and low overall survival." (PMID 33149754, 2020). "Recent studies have indicated that PTGS2 genetic variation is associated with breast cancer susceptibility." (PMID 23374284, 2013). "In the present study, we identified single-nucleotide polymorphisms (SNPs) in the PR and 3'-UTR of the PTGS2 gene and evaluated their association with breast cancer occurrence among Brazilians." (PMID 21059239, 2010). "The second step was a case-control study with 318 patients and 273 controls designed to evaluate PTGS2 genotype- or haplotype-associated risk of breast cancer." (PMID 21059239, 2010). "We have therefore genotyped five single-nucleotide polymorphisms (SNPs) in the PTGS2 gene in the breast cancer cases and controls nested within the Nurses' Health Study (NHS)." (PMID 17214885, 2007). "The rs5275 polymorphism in the 3' untranslated region of the PTGS2 gene was associated with a decrease in breast cancer risk." (PMID 17214885, 2007). "Only the rs5275 polymorphism in the 3' UTR of the PTGS2 gene showed an association with risk of breast cancer and was therefore subsequently genotyped in the NHS2 and WHS." (PMID 17214885, 2007). "Furthermore, overexpression of PTGS2 in patients with breast cancer is associated with a worse prognosis." (PMID 23374284, 2013). "Examination of how the PTGS2 enzyme works in the breast, and in particular neoplastic breast cells, could shed light on its relation to breast cancer risk." (PMID 17214885, 2007). "We hypothesize that polymorphisms in this gene could influence the risk of breast cancer, through altering the levels of expression or activity of the PTGS2 enzyme." (PMID 17214885, 2007). "We genotyped the five most common polymorphisms (rs20417, rs5277, rs20432, rs5275, and rs4648298) in the Nurses' Health Study (1,270 cases, 1,762 controls) to test the hypothesis that polymorphisms in PTGS2 are associated with breast cancer risk, using logistic regression analyses." (PMID 17214885, 2007). "Breast cancer exhibits specific levels of COX2 (PTGS2) and MMP1, which facilitate vascular remodeling and extravasation." (PMID 41596524, 2026). "The antiproliferative and pro-apoptotic effects of specific COX-2 inhibitors in cancer cells from solid tumours have been investigated, as PTGS2 gene is overexpressed in breast carcinoma, melanoma, pancreatic, prostate, colon and lung cancer." (PMID 40444088, 2025). "Its potential as a therapeutic target is further supported by interventions such as quercetin, which has been shown to ameliorate depression-related symptoms in breast cancer models through multi-faceted mechanisms that include the suppression of PTGS2." (PMID 41150784, 2025). "This indicated that LOC610012 inhibits the activity of canine mammary tumor cells through the PTGS2/EP3&GSK-3β axis." (PMID 40643495, 2025).
breast carcinoma (continued). "It is vital to identify the likely biological processes and cellular functions by which PTGS2/ESR2/EGFR/JUN/MMP2 genes’ signature exhibited their tumorigenic effect in breast cancer." (PMID 39707884, 2024). "Our search demonstrated that the PTGS2 protein levels in breast cancer patients’ samples revealed positive staining (medium to high intensity) in 70% of the examined tissues." (PMID 39707884, 2024). "Breast cancer patients with elevated expression of PTGS2/ESR2/EGFR/JUN/MMP2 genes’ signature displayed significantly poor OS (P = 0.026) and DMFS (P = 0.0066) and consequently unfavorable prognosis." (PMID 39707884, 2024). "A significant (P < .0001) positive Pearson’s pairwise correlation with different strength intensities was observed between PTGS2 and the other four genes in the heatmaps representing all breast cancer patients." (PMID 39707884, 2024). "Combining the results of network pharmacology with other bioinformatics databases suggests that myrrh’s active components exert anti-cancer effects by regulating genes involved in breast cancer pathogenesis, particularly PTGS2, EGFR, ESR2, MMP2, and JUN." (PMID 39707884, 2024). "To further validate our assortment of these genes, we ran another analysis to map the correlation between PTGS2 and the other eight candidates in a large cohort of 5696 breast cancer patients’ samples using the same bcGenExMiner v5.0 platform." (PMID 39707884, 2024). "Hub genes are involved in the generation of cancer stem cells (CSCs) and are related to inflammatory mediators, including CXCL8, IL1-β and PTGS2, which promote inflammation and breast cancer growth, metastasis, and development." (PMID 37138170, 2023). "CXCL8 plays a role in angiogenesis, and IL-1β enhances tumor inflammation, activates the β-catenin signaling pathway and induces EMT in breast cancer cells in addition to the expression of PTGS2." (PMID 37138170, 2023). "Not only is the expression of PTGS2 remarkably upregulated during inflammation, but also in various tumors such as gallbladder, and breast cancers." (PMID 35910372, 2022). "Through comparison each gene of our gene signature with existing studies separately, we found that there are many studies on the association between gene PTGS2, gene SQSTM1 and breast cancer." (PMID 35436939, 2022). "In fact, a study found that PTGS2 is involved in the formation of cerebrospinal fluid tumour cells in brain metastatic breast cancer, which also indicates that PTGS2 is closely related to brain metastasis." (PMID 33926551, 2021). "Hypoxia has also been found to affect the expression of the gene encoding EDN1 in U87 glioma cells and the genes encoding PTGS2 and VEGFA in breast cancer and melanoma cells." (PMID 34098948, 2021). "Further validation of gene expression by using GEPIA revealed that the mRNA expression of MMP9 was significantly higher in breast cancer tissues than in normal tissues, whereas the mRNA expression of PTGS2 showed the opposite." (PMID 34335799, 2021). "Several of the LXRE genes predicted increased regression-free survival in breast cancer subjects, among which Ptgs2, Mfge8, Anxa1, Spp1, S100a9 and Cd14 are biomarkers for MDSC and Treg cells." (PMID 33780491, 2021). "In bone, the hypoxia inducible factor-1 alpha (HIF1A) has a promoting effect on breast cancer metastasis by upregulating prostaglandin endoperoxide synthase-2 (PTGS2, also known as COX-2)." (PMID 33830428, 2021). "Cyclooxygenase 2 (COX-2), also known as prostaglandin-endoperoxide synthase 2 (PTGS2), a key enzyme in prostaglandin synthesis, is known to play a role in carcinogenesis and tumor progression, including breast cancer." (PMID 34249719, 2021). "In the previous step, we performed a single gene characterization of the hub gene related to the overall survival rate of breast cancer, and we found that all PTGS2, ESR1, and FOS were enriched in the PPAR signaling pathway." (PMID 33149754, 2020).